RNU6-769P (RNA, U6 small nuclear 769, pseudogene)
Gene: Small nuclear RNA gene on chromosome 12 (50,633,273 to 50,633,376, forward strand). Ensembl gene ENSG00000207136.
Homologues: Orthologues: chimpanzee U6 (99% identical), macaque U6 (95% identical), guinea pig U6 (77% identical), rabbit U6 (73% identical), mouse Gm23981 (72% identical), mouse Gm26061 (68% identical), rat LOC120095363 (68% identical), rat LOC120100195 (63% identical). Paralogues in human: RNU6-73P (89% identical), RNU6-1117P (88% identical), RNU6-38P (88% identical), RNU6-639P (88% identical), RNU6-20P (88% identical), RNU6-1011P (87% identical), RNU6-1145P (87% identical), RNU6-12P (87% identical), RNU6-13P (87% identical), RNU6-16P (87% identical), RNU6-25P (87% identical), RNU6-29P (87% identical), and 1287 more.